LEP (leptin)
Diseases named in the same sentence as LEP in open-access papers (continued):
Sharing a sentence is not in itself a finding about the gene and the disease.
psoriasis (continued). "The adipokine milieu in patients with psoriasis is similar to that of prediabetic subjects, who present with lower levels of adiponectin and increased levels of leptin and resistin compared to healthy controls." (PMID 36012327, 2022). "Leptin is an adipocyte-derived cytokine that modulates inflammatory responses in various pathological conditions, including psoriasis." (PMID 35457132, 2022). "The levels of leptin and resistin are increased in patients with psoriasis and are positively correlated with disease severity, while the levels of lipocalin are decreased." (PMID 36405690, 2022). "Significant deviations from normal serum leptin concentration are currently being investigated in psoriasis." (PMID 35628271, 2022). "One study reported that leptin levels were higher in obese patients with psoriasis than those of normal-weight patients." (PMID 34367173, 2021). "Psoriasis is a disease with a proinflammatory base, in which an increased expression of leptin, tumor necrosis factor alpha (TNF-α), interleukin (IL) IL-12/23, IL-6, is observed." (PMID 33562571, 2021). "Apart from aggravating the inflammatory cascade, leptin also induces keratinocyte proliferation, which is a crucial step in the development of the characteristic skin lesions in psoriasis; at the same time, it drives T cells toward the Th-1 phenotype." (PMID 33499118, 2021). "Increased leptin levels are observed in obese people and in patients with psoriasis, and are positively correlated with severity of psoriasis." (PMID 34367173, 2021). "Firstly, numerous findings confirm a significantly higher concentration of leptin among psoriasis patients, especially in its moderate and acute form, in which treatment with anti-cytokine agents is recommended." (PMID 33562571, 2021). "In the present study elevated leptin levels were found in patients with psoriasis which is consistent to previous publications." (PMID 33927259, 2021). "Of note, some studies indicated a decrease in peripheral levels of leptin after systemic therapy of psoriasis." (PMID 33008429, 2020). "Herein, we also aim to present the current knowledge concerning the role of enhanced leptin levels in the pathomechanisms of psoriasis and selected skin diseases." (PMID 33008429, 2020). "There are numerous studies concerning adipokine levels in a course of psoriasis, and these observations comprised not only leptin but also resistin, adiponectin, and others." (PMID 33008429, 2020). "Recently, a positive correlation between serum leptin concentration and the severity of psoriasis, which is evaluated by the Psoriasis Area and Severity Index (PASI), was also put forward." (PMID 33597945, 2020). "The CIMT is positively correlated with serum leptin levels in patients with psoriasis and premenopausal systemic lupus erythematosus patients." (PMID 32300333, 2020). "Herein, we present the current knowledge concerning the role of leptin in psoriasis and selected skin diseases." (PMID 33008429, 2020). "Levels of leptin and resistin were higher in patients with psoriasis than in healthy people, and it strongly correlated with disease severity." (PMID 32443588, 2020). "The previous studies revealed the role of leptin in wound healing, hair cycle, and pathogenesis of skin diseases like psoriasis, lupus erythematosus, and skin cancers." (PMID 33008429, 2020). "In obese men, LEP has been proposed as a pathogenetic cofactor of psoriasis as a stimulating factor for the local inflammatory process moreover its possible involvement in hypersensitivity reactions was suggested." (PMID 33316917, 2020). "In patients with psoriasis, elevated levels of leptin, chemerin, visfatin and resistin have been found, with decreased levels of protective adipokines: adiponectin and omentin." (PMID 33187195, 2020). "Making the picture more complicated, another study showed that the levels of leptin were decreased in psoriasis." (PMID 33260746, 2020).
psoriasis (continued). "A positive correlation between serum leptin concentration and the severity of psoriasis lesions, evaluated with the Psoriasis Area and Severity Index (PASI), was also found." (PMID 33008429, 2020). "Greater expression of leptin and leptin receptor was observed in the epidermis of individuals with a severe form of psoriasis in comparison to the patients with mild to moderate form of the disease." (PMID 33008429, 2020). "There are numerous studies concerning serum adipokine levels during the course of psoriasis, and these observations comprise not only leptin but also resistin, adiponectin, and other inflammatory cytokines." (PMID 33597945, 2020). "It has also been postulated that leptin induces psoriasis skin to produce amphiregulin, which is known to drive autocrine keratinocyte proliferation in culture." (PMID 31316526, 2019). "Elevated levels of leptin and resistin and lower levels of adiponectin in serum adjusted for BMI have been shown in patients with PsA and psoriasis in comparison with healthy controls." (PMID 30635024, 2019). "Leptin can increase keratinocyte proliferation and pro-inflammatory protein secretion, which are characteristics of psoriasis, while the secretion of adiponectin, which is putatively anti-inflammatory, is reduced in the obese state." (PMID 30703100, 2019). "All concluded that leptin and resistin had higher levels in patients with psoriasis, compared to the healthy control population, and that adiponectin levels were lower in psoriasis patients than in healthy patients." (PMID 31275060, 2019). "With respect to leptin and resistin, both of these adipokines are present in high levels in obese persons with psoriasis." (PMID 31275060, 2019). "IR is strongly influenced by the activity of pro-inflammatory adipocytokines, as TNF-α, IL-6, and leptin, inducing a state of persistent low-grade inflammation that underlies the physiopathology of both NAFLD and psoriasis." (PMID 31540048, 2019). "At the same time, previous reports showed that the adipokines-derived cytokines including leptin are present in high concentrations in patients with psoriasis." (PMID 31157131, 2019). "In fact, serum or plasma levels of leptin are higher in patients with psoriasis as compared to the healthy controls." (PMID 31491865, 2019). "The presence of elevated leptin inhibits the differentiation of regulatory T cells, which maintain tolerance and prevent psoriasis, in adipose tissue." (PMID 31491865, 2019). "Stimulated by activated macrophages in adipose tissue, adipocytes secrete adipokines such as IL-6, TNF-α, visfatin and leptin, which also play an important role in the pathogenesis of psoriasis." (PMID 29696068, 2018). "High circulating leptin levels have been found in psoriasis patients possibly deriving both from adipose tissue in obese patients and inflammation." (PMID 29696068, 2018). "Inflammatory cytokines involved in development of insulin resistance, such as TNF-α, IL-6 together with leptin and adiponectin, were also found in psoriasis." (PMID 30011841, 2018). "Leptin is shown to be elevated in patients with psoriasis, to correlate with psoriasis disease severity and with indices of subclinical atherosclerosis." (PMID 29910818, 2018). "Serum leptin level has also been found to correlate with subclinical atherosclerosis (carotid intima-media wall thickness) in psoriasis patients." (PMID 29065479, 2017). "Treatment of psoriasis patients with TNF-α inhibitors has been shown to suppress serum leptin levels." (PMID 29065479, 2017). "Previously, serum leptin levels have been shown to be elevated in psoriasis patients and correlate with psoriasis disease severity." (PMID 29065479, 2017). "The presented data support general opinion that cytokines produced by adipocytes (adiponectin, leptin, and resistin) are involved in the pathogenesis of MS as well as in the pathogenesis of psoriasis." (PMID 28097156, 2016).
psoriasis (continued). "Some authors also described elevated serum leptin levels in their patients with systemic lupus erythematosus or psoriasis in comparison with healthy controls." (PMID 24900992, 2014). "Angiogenetic processes precede the epidermal hyperplasia in psoriasis, indicating possible involvement of leptin in the pathogenesis of psoriasis." (PMID 24600521, 2014). "Leptin has been correlated with the histogenesis of psoriasis and involved in alterations of endothelial cell morphology and epithelial hyperplasia." (PMID 24600521, 2014). "Compared with those in both healthy and psoriasis controls, the circulating concentrations of leptin and omentin in patients with PsA were higher, but the levels of adiponectin were lower." (PMID 23144698, 2012). "In Cerman's study a significant increase in serum leptin in severely affected psoriasis patients was shown in comparison to mild to moderately affected patients and controls." (PMID 23144698, 2012). "Assessed by immunohistochemistry, the expressions of leptin and its receptor in skin biopsy samples were only increased in severely affected psoriasis patients." (PMID 23144698, 2012). "Obese people are more likely to acquire psoriasis, and their plasma leptin levels are higher." (PMID 41226468, 2025). "Leptin enhances Th17-mediated inflammation by promoting the differentiation of naïve T cells into Th17 cells, leading to an increased production of IL-17, a cytokine pivotal in psoriasis pathogenesis." (PMID 40277935, 2025). "Moreover, higher leptin levels have been reported in the blood and tissues of patients with psoriasis." (PMID 39598018, 2024). "Elevated levels of leptin are observed in obese individuals and patients with psoriasis, and are positively correlated with the severity of psoriasis, and can be reduced by acitretin, a systemic anti‐inflammatory drug for psoriasis." (PMID 38174774, 2024). "Moreover, leptin, a hormone involved in metabolism regulation, is found in higher concentrations in psoriasis patients, suggesting its role in the disease’s metabolic and inflammatory processes." (PMID 39598018, 2024). "The most studied adipokines in psoriasis are adiponectin, leptin, and resistin." (PMID 37895330, 2023). "Within the scope of psoriasis research, leptin emerges as a notable inhibitor for Treg cells." (PMID 38035065, 2023). "Additionally, adipokines and leptin, reflecting the overall level of inflammation, can be used as screening and predictive indicators for psoriasis comorbidities." (PMID 36837593, 2023). "Previous studies suggest that adiponectin may have anti-inflammatory effects in psoriasis, slowing the development of the disease, while leptin and resistin may increase inflammation, exacerbating the symptoms of psoriasis." (PMID 36675592, 2023). "According to the data available in the current literature, leptin might contribute to the development of psoriasis." (PMID 37047363, 2023). "Leptin and resistin are found at higher levels in psoriasis patients." (PMID 36766689, 2023). "It has also been described that the major adipokines, leptin, resistin, and adiponectin, may be involved in the pathogenesis of psoriasis." (PMID 36675592, 2023). "Furthermore, excessive secretions of adipokines and hypoxia, especially leptin and adiponectin, are a crucial aspect of the pathophysiological link between psoriasis and obesity." (PMID 38004054, 2023). "This fact may explain why leptin levels have consistently increased in obese patients and patients with psoriasis, and its elevation correlates directly with PASI score and BMI." (PMID 35886846, 2022). "Serum leptin levels in patients with psoriasis are reported to be elevated." (PMID 35457132, 2022). "Disturbances in levels of adipokines (e.g. decreased levels of adiponectin and omentin and increased levels of leptin and resistin) may play a role in increasing the prevalence of cardiovascular disease in psoriasis patients." (PMID 36202827, 2022).
psoriasis (continued). "In addition, leptin can affect dendritic and T helper cells responsible for immunity response in psoriasis." (PMID 35886846, 2022). "However, these authors do not wholly negate the possibilities of changes in the concentration of leptin under the influence of drugs used in psoriasis, at a time when the weight of the patients also decreases." (PMID 33562571, 2021). "Authors concluded that improvement of adiponectin, leptin and resistin serum concentrations are linked to effective psoriasis treatment, and this effect is not specific to any type of the therapy." (PMID 33927259, 2021). "Interestingly, increased leptin levels have also been detected in patients with psoriasis independently of BMI." (PMID 33499118, 2021). "Moreover, leptin mRNA expression in the subcutaneous adipose tissue also positively correlated with the severity of psoriasis and the BMI in obese psoriatic patients suggesting that leptin-induced signaling mediates both local as well as systemic changes." (PMID 34685457, 2021). "Apart from an undeniable connection between an increased concentration of leptin and obesity, an excessive expression of this adipokine is observed in psoriasis, which is a disease with a proinflammatory base, during which the balance between pro- and anti-inflammatory cytokines is disturbed." (PMID 33562571, 2021). "The systemic anti-inflammatory drug, acitretin, used to treat psoriasis, reduces leptin levels." (PMID 34367173, 2021). "In contrast, the case-control study on the Turkish population did not confirm the association between the LEP G-2548A polymorphism and the incidence of psoriasis." (PMID 34445769, 2021). "Interestingly, a Th1/Th17 pattern was also seen in inflammatory skin conditions such as psoriasis or lupus, possibly because Leptin suppresses regulatory T cells and enhances Th17 cells." (PMID 34017323, 2021). "Higher leptin and resistin and lower adiponectin concentrations in psoriasis can be a proof of close relationship between skin inflammation and metabolic status in psoriasis patients." (PMID 33927259, 2021). "Of note, some studies demonstrated robustly decreased levels of leptin in peripheral tissues after systemic therapy for psoriasis, such as using cyclosporine-A, suggesting a close relationship between serum levels of leptin and the pathological progression or regression of psoriasis." (PMID 33597945, 2020). "Recent studies showed elevated circulating leptin levels in patients with psoriasis." (PMID 32823524, 2020). "However, the role of leptin in the pathogenesis of skin diseases with the particular concern of psoriasis is still investigated." (PMID 33008429, 2020). "Expression of leptin and its receptor was significantly higher in the involved skin of psoriasis." (PMID 32823524, 2020). "Studies on animal models broaden our knowledge of the potential role of leptin in psoriasis." (PMID 33008429, 2020). "Regarding histological studies, leptin and leptin receptor expression were significantly higher in the skin of severe psoriasis patients with normal BMI than in patients with mild-moderate psoriasis and controls." (PMID 33260746, 2020). "Among various adipokines, leptin shows increased levels in sera of patients with psoriasis." (PMID 32987907, 2020). "Increased leptin levels are correlated with the severity of psoriasis." (PMID 32987907, 2020). "High levels of resistin and leptin have been found in obese psoriasis patients." (PMID 31417571, 2019). "Further, the plasma levels of leptin and resistin are related to the severity of psoriasis." (PMID 31275060, 2019). "Although there has been contradicting studies showing leptin levels that are both increased or decreased in patients with psoriasis, a recent meta-analysis of 26 studies concluded that patients with psoriasis had higher leptin concentrations compared to the control population." (PMID 31316526, 2019). "The role of leptin in psoriasis is clearly related to its proinflammatory actions." (PMID 31824416, 2019).
psoriasis (continued). "Moreover, leptin levels have been found to be higher in psoriasis, Behçet's syndrome, skin tags, and acanthosis nigricans." (PMID 31824416, 2019). "In addition a positive correlation between leptin and the severity of psoriasis has been observed, while lower levels of adiponectin have been found among psoriasis patients." (PMID 29680995, 2018). "This could be explained by the concept of “psoriatic march” regarding psoriasis as a chronic systemic inflammatory disorder, with not only the classical markers for systemic inflammation, but also elevated resistin and leptin levels." (PMID 30011841, 2018). "It is assumed that adiponectin and leptin may be the links between psoriasis and their comorbidities." (PMID 28097156, 2016). "In this context, the already published data support the assumption that cytokines produced by adipocytes, leptin, and adiponectin could be involved in the pathogenesis of psoriasis." (PMID 26166954, 2015). "It seems that inflammatory mediators may be involved in insulin resistance, such as TNF-α, Il-6, leptin, adiponectin, mediators that are also disturbed in psoriasis (further detailed below)." (PMID 25713604, 2014). "Psoriasis patients have high levels of leptin and these high levels may derive both from the adipose tissue in obese patients and from inflammation." (PMID 25713604, 2014). "Activated macrophages in the adipose tissue stimulate adipocytes to secrete adipocytokines (adipokines), such as TNF-α, IL-6, leptin, and visfatin, which may also play a role in the pathogenesis of psoriasis." (PMID 25713604, 2014). "Thus, the prevalence of SAT in women could explained, at least in part, the higher levels of leptin in women with psoriasis compared to affected men observed in our study population." (PMID 40740781, 2025). "Moreover, adipose tissue-derived hormones, known as adipokines, including leptin and adiponectin, exert modulatory effects on immune responses and may contribute to the link between psoriasis and metabolic abnormalities." (PMID 38344577, 2024). "Leptin’s ability to promote increased secretion of pro-inflammatory cytokines by keratinocytes may explain the correlation found between leptin plasma levels and psoriasis severity." (PMID 36766689, 2023). "Leptin could be used to measure the severity and recurrence of psoriasis." (PMID 37047363, 2023). "Understanding leptin's immunomodulatory function may help to explain its link to psoriasis." (PMID 31316526, 2019). "In addition, tissue levels of leptin are increased in the skin of patients with psoriasis." (PMID 31491865, 2019). "Leptin deficiency has been shown to counteract psoriasis-like skin inflammation in a mouse model, while leptin stimulation of human kerotinocytes has shown to increase the proliferation and to induce secretion of several pro-inflammatory proteins, two of the characteristics of psoriasis." (PMID 29680995, 2018). "Moreover, increased leptin expression may induce increased levels of pro-inflammatory cytokines leading to exacerbation of psoriasis." (PMID 29065479, 2017). "It has been suggested that leptin may be a marker of severity of psoriasis." (PMID 28097156, 2016). "Therefore, we could proclaim that elevated levels of proinflammatory CRP and leptin and decreased levels of anti-inflammatory adiponectin reflect an ongoing inflammatory process in patients with psoriasis." (PMID 26166954, 2015). "In addition, serum leptin levels, tissue leptin and leptin receptor expression showed a positive correlation with disease duration in patients with psoriasis The authors concluded that leptin might serve as a marker of severity and chronicity in psoriasis." (PMID 23144698, 2012). "In our research, we analyzed how clinical and inflammatory aspects, such as BMI, triglycerides, glycemia, leptin, SII and the cytokines IL-17A and IL-23, influence quality of life as measured by DLQI, in psoriasis patients after one year of treatment." (PMID 40003621, 2025).